TMEFF1 (transmembrane protein with EGF like and two follistatin like domains 1)
Description:
Neuron-specific restriction factor that prevents herpes simplex virus 1 (HHV-1) infection in the brain by blocking viral entry. Also able to restrict herpes simplex virus 2 (HHV-2) infection, although to a lesser extent. Acts by preventing the association between the viral glycoprotein D (gD) and its cell surface receptor NECTIN1, thereby inhibiting fusion of the virus and the cell membrane. Also able to prevent the association between the viral glycoprotein B (gB) and MYH9/NMMHC-IIA and MYH10/NMMHC-IIB receptors. May be a tumor suppressor in brain cancers.
Synonyms: TR-1; C9orf2; H7365; CT120.1
Tractability: Antibody: UniProt places it where antibodies can reach, with high confidence; its Gene Ontology location is reachable by antibodies, with high confidence; UniProt predicts a signal peptide or a membrane-spanning region. PROTAC: ubiquitination databases record sites on it; its protein half-life has been measured.
Gene: Protein-coding gene on chromosome 9 (100,473,121 to 100,577,636, forward strand). Ensembl gene ENSG00000241697.
Subcellular location: Cell membrane
Gene Ontology:
Molecular function: receptor ligand inhibitor activity
Biological process: host-mediated suppression of symbiont invasion
Cellular component: plasma membrane
Genetic constraint (gnomAD): Loss-of-function variants: 20 observed, 43.94 expected, observed/expected ratio (o/e) 0.46, 90% interval 0.32 to 0.66. The upper end of that interval is the gene's LOEUF score, 0.66, which puts it in group 2 of 6, group 1 being the genes least tolerant of losing a copy. Missense variants: 411 observed, 445.22 expected, observed/expected ratio (o/e) 0.92, 90% interval 0.85 to 1. Synonymous variants: 162 observed, 145.17 expected, observed/expected ratio (o/e) 1.12, 90% interval 0.98 to 1.27.
Homologues: Orthologues: pig TMEFF1 (99% identical), mouse Tmeff1 (93% identical), rat Tmeff1 (93% identical), chimpanzee TMEFF1 (86% identical), dog TMEFF1 (85% identical), macaque TMEFF1 (85% identical), guinea pig TMEFF1 (84% identical), tropical clawed frog tmeff1 (73% identical). Paralogues in human: TMEFF2 (48% identical), LAMA3 (27% identical), LAMA2 (27% identical), LAMA1 (26% identical), LAMA5 (26% identical), LAMB2 (25% identical), LAMB1 (24% identical), USH2A (24% identical), LAMC1 (24% identical), HSPG2 (23% identical), LAMB4 (23% identical), LAMC3 (21% identical), and 15 more.
Diseases named in the same sentence as TMEFF1 in open-access papers:
TMEFF1 is named in the same sentence as 43 diseases in open-access papers, as found by Europe PMC text mining. Sharing a sentence is not in itself a finding about the gene and the disease. The quoted sentences say what the papers report.
endometrial carcinoma (4 papers, 2021 to 2025). A malignant tumor arising from the epithelium that lines the cavity of the uterine body. "Our results showed that TMEFF1 was highly expressed in endometrial carcinoma, that its expression was closely associated with FIGO stage and lymph node metastasis, and that it was an independent predictor of survival." (PMID 34475991, 2021). "In addition to the age of diagnosis, FIGO stage, degree of differentiation, depth of myometrial invasion, lymph node metastasis and PR and ER status, high expression of TMEFF1 also affected the overall survival of patients with endometrial carcinoma and was an independent risk factor for prognosis." (PMID 34475991, 2021). "TMEFF1 is highly expressed in endometrial cancer and is closely related to FIGO staging and lymph node metastasis." (PMID 35771155, 2022). "According to reports, TMEFF1 can promote the malignant behaviors of ovarian cancer and endometrial cancer cells by activating MAPK and PI3K/AKT signaling pathways." (PMID 35771155, 2022). "As an independent prognostic factor for endometrial carcinoma, TMEFF1 promotes the invasion and migration of endometrial carcinoma cells, activates the PI3K/AKT and MAPK signaling pathways, and participates in the regulation of EMT." (PMID 34475991, 2021). "Based on the results of the current study, we confirmed that TMEFF1 plays an important role in endometrial carcinoma." (PMID 34475991, 2021). "The high expression rate of TMEFF1 in endometrial carcinoma was 57.33% (43 of 75), which was significantly higher than that of normal endometrial tissue (25.00% [9 of 36]) (P=0.001)." (PMID 34475991, 2021). "We first compared the expression levels of TMEFF1 in different endometrial carcinoma cell lines (Ishikawa, HEC-1-B, and HEC-1-A) and then selected Ishikawa and HEC-1-B cell lines with high TMEFF1 expression for knockdown of the TMEFF1 gene." (PMID 34475991, 2021). "Accordingly, we use several bioinformatics databases to analyze the expression of TMEFF1 in endometrial carcinoma and functional regulatory networks." (PMID 34475991, 2021). "Transwell assays revealed that TMEFF1 knockdown in Ishikawa and HEC-1-B cell lines significantly reduced cell invasiveness, indicating that TMEFF1 promotes the invasion of endometrial carcinoma cells." (PMID 34475991, 2021). "We additionally investigated the effect of TMEFF1 on the malignant behavior of endometrial carcinoma and its mechanism, providing a theoretical basis for the early diagnosis and immunotherapy of endometrial carcinoma." (PMID 34475991, 2021). "We found that TMEFF1 is highly expressed in endometrial carcinoma tissues and promotes the invasion and migration of endometrial carcinoma cells." (PMID 34475991, 2021). "Cell scratch experiments showed that the migration ability of Ishikawa and HEC-1-B cells decreased after knockdown of the TMEFF1 gene, indicating that TMEFF1 promotes the migration of endometrial carcinoma cells." (PMID 34475991, 2021). "Through the cBioPortal database, it was found that TMEFF1 is genetically altered in endometrial cancer, with alterations mainly including amplifications, deep deletions, truncating mutations and missense mutations." (PMID 34475991, 2021). "The analysis of TMEFF1 in 174 endometrial cancer tissues and 91 normal endometrial tissues indicated that TMEFF1 mRNA was significantly highly expressed in endometrial cancer (P < 0.01)." (PMID 34475991, 2021). "We confirmed that TMEFF1 is an oncogene in ovarian cancer and endometrial carcinoma." (PMID 38468232, 2024).
endometrial carcinoma (continued). "The positive expression rate of TMEFF1 in endometrial carcinoma was 82.67% (62 of 75 cases), which was significantly higher than that of atypical hyperplasia (62.50% [15 of 24]) and normal endometrial tissue (58.33% [21 of 36]) (P=0.039 and 0.006, respectively)." (PMID 34475991, 2021). "A number of questions remain, such as the expression of TMEFF1 in endometrial carcinoma and whether it plays a role in suppressing or promoting cancer." (PMID 34475991, 2021). "In this study, we sought to explore the role of TMEFF1 in endometrial carcinoma and its mechanisms." (PMID 34475991, 2021). "To further explore the functional targets of TMEFF1 in endometrial cancer, we analyzed the kinases, miRNAs and transcription factors that could serve as targets of genes positively related to TMEFF1 by GSEA." (PMID 34475991, 2021). "Thus, TMEFF1 is involved in the regulation of EMT and affects the malignant behavior of endometrial carcinoma cells." (PMID 34475991, 2021). "To further explore the mechanism underlying the effect of TMEFF1 on the invasion and migration of endometrial carcinoma cells, we used western blot to determine the changes in the key EMT proteins E-cadherin, Vimentin, MMP2, and MMP9 between before and after TMEFF1 knockdown." (PMID 34475991, 2021). "There has been no research into TMEFF1 in endometrial carcinoma." (PMID 34475991, 2021).
ovarian carcinoma (4 papers, 2021 to 2024). A malignant neoplasm originating from the surface ovarian epithelium. "In this study, we found that ST14 and TMEFF1 were overexpressed and interacted in ovarian cancer and both are independent risk factors for prognosis." (PMID 38468232, 2024). "Multivariate Cox regression analysis found that ST14 expression and TMEFF1 expression were independent risk factors affecting the prognosis of patients with ovarian cancer (P = 0.026, 0.002)." (PMID 38468232, 2024). "Previous studies have found that TMEFF1 is highly expressed in ovarian cancer and is an independent risk factor for prognosis." (PMID 34475991, 2021). "In this study, we detected the expression of ST14 and TMEFF1 in 130 different ovarian cancer tissues through immunohistochemistry." (PMID 38468232, 2024). "We revealed that TMEFF1 overexpression facilitated ovarian cancer cell proliferation, migration, and invasion." (PMID 38468232, 2024). "In summary, this shows that ST14 and TMEFF1 can effectively predict the prognosis of ovarian cancer patients." (PMID 38468232, 2024). "The function of ST14-TMEFF1 in proliferation, invasion and metastasis of ovarian cancer will be detected by cytological experiments, which will provide a new research direction to explore the interaction between ST14 and TMEFF1 in ovarian cancer." (PMID 38468232, 2024). "We determined ST14 and TMEFF1 were highly expressed in ovarian cancer, indicating a higher degree of tumor malignancy and a worse prognosis." (PMID 38468232, 2024). "Overall, high expression of ST14 and TMEFF1 in ovarian cancer predicts higher tumor malignancy and a worse prognosis." (PMID 38468232, 2024). "TMEFF1 is a new protein involved in the physiological functions of the central nervous system, and we previously reported TMEFF1 can promote ovarian cancer." (PMID 38468232, 2024). "In order to further detect the role of ST14 and TMEFF1 interaction in ovarian cancer cells, MTT, Transwell and Wound healing assays were performed." (PMID 38468232, 2024). "In this study, through immunohistochemistry, immunoprecipitation and double-labeled immunofluorescence assays we confirmed ST14 and TMEFF1 were expressed positively correlated, co-precipitated and co-localized in ovarian cancer." (PMID 38468232, 2024). "Through immunoprecipitation, we found that ST14 and TMEFF1 interact in the ovarian cancer cells CAOV3, OVCAR3, and SKOV3." (PMID 38468232, 2024). "ST14 can regulate TMEFF1 expression to promote proliferation, migration and invasion of ovarian cancer cells." (PMID 38468232, 2024). "Through analysis of the GEPIA website, it was also found that in ovarian cancer (TCGA tumor) and normal ovaries (GTEx), the expression levels of TMEFF1 and ST14 are positively correlated (R = 0.32, P = 1.1e-13)." (PMID 38468232, 2024). "High TMEFF1 expression predicts shorter overall survival in ovarian cancer patients, and its ectopic expression in vitro promotes malignant progression of ovarian cancer cells." (PMID 35771155, 2022). "A recent research indicated that TMEFF1 is highly expressed in ovarian cancer tissues and cell lines, and its high expression predicts a shorter overall survival period for patients with ovarian cancer." (PMID 35771155, 2022). "In conclusion, MIR503HG acted as a tumor suppressor lncRNA in ovarian cancer by suppressing transcription factor SPI1-mediated transcriptional activation of TMEFF1." (PMID 35771155, 2022). "TMEFF1 promotes the malignant behavior of ovarian cancer by activating the PI3K/AKT and MAPK pathways." (PMID 34475991, 2021). "Work showed that TMEFF1 was highly expressed in ovarian cancer tissues, promoted the malignant behavior of cancers, and was closely associated with the occurrence and progression of malignant cancers." (PMID 34475991, 2021). "Therefore, in this study, we will explore the interaction between ST14 and TMEFF1 and their relationship with prognosis in ovarian cancer." (PMID 38468232, 2024).
ovarian carcinoma (continued). "Thus, the specific mechanisms of interactions between ST14 and TMEFF1 affecting ovarian cancer still need to be studied in depth." (PMID 38468232, 2024). "We first discovered the interaction of TMEFF1 with ST14 in ovarian cancer." (PMID 38468232, 2024). "In previous studies, we found that TMEFF1 is an oncogene in ovarian cancer." (PMID 38468232, 2024). "We speculate that the relationship between ST14 and TMEFF1 in ovarian cancer could become a potential target for anti-cancer therapy." (PMID 38468232, 2024). "ST14 and TMEFF1 co-localize and interact with each other in ovarian cancer." (PMID 38468232, 2024). "MIR503HG could bind to the transcription factor SPI1 to prevent SPI1 from binding to the TMEFF1 promoter region, thereby suppressing the tumorigenicity of ovarian cancer cells." (PMID 35771155, 2022). "The role of TMEFF1 in brain, endometrial and ovarian cancers has been investigated." (PMID 35771155, 2022). "In addition, overexpression of TMEFF1 promotes the proliferation, migration and invasion of ovarian cancer cells, and inhibits cell apoptosis." (PMID 35771155, 2022). "Butorphanol treatment suppressed the viability, migration, invasion and colony formation of ovarian cancer cells, and it was found that Butorphanol might play its role by decreasing TMEFF1 expression." (PMID 35771155, 2022). "GEPIA website analysis showed that the expression of TMEFF1 mRNA was significantly increased in ovarian cancer, uterine corpus endometrial carcinoma, and uterine carcinosarcoma, but decreased in glioblastoma multiforme, acute myeloid leukemia, and thyroid carcinoma." (PMID 34475991, 2021). "Therefore, blocking the interaction site of ST14 and TMEFF1 protein may become a potential target for the treatment of ovarian cancer." (PMID 38468232, 2024). "The expression of TMEFF1 mRNA was significantly increased in cervical cancer, colorectal cancer, esophageal cancer, gastric cancer, head and neck cancer, kidney cancer, lung cancer, myeloma, ovarian cancer, pancreatic cancer, prostate cancer and sarcoma but decreased in brain and CNS cancer." (PMID 34475991, 2021). "Among all 91 cases of ovarian cancer, 49 total cases showed high expression of ST14 and TMEFF1 at the same time, whereas 15 cases showed low expression at the same time." (PMID 38468232, 2024). "In previous studies, we also found that TMEFF1 promotes the expression of N-cadherin, Vimentin, MMP2, and MMP9 in ovarian cancer cells, inhibits the expression of E-cadherin, and participates in the EMT process." (PMID 38468232, 2024). "Through immunofluorescence double staining, we found that the co-localization of TMEFF1 and ST14 in the cell membrane of different ovarian tissues and ovarian cancer cell line CAOV3." (PMID 38468232, 2024). "A follow-up of patients with ovarian cancer (as of January 30, 2020) with univariate Kaplan–Meier analysis showed that the high expressions of ST14 and TMEFF1 were both correlated with shortened OS (P = 0.003; 0.001, respectively)." (PMID 38468232, 2024). "Western blot results showed that knocking down ST14 in ovarian cancer CAOV3 and SKOV3 cell lines also decreased the expression of TMEFF1 (P < 0.05), indicating that ST14 regulates the expression of TMEFF1 in these cells." (PMID 38468232, 2024). "We found that TMEFF1 promotes activation of PI3K/AKT and MAPK pathways in ovarian cancer to promote the malignant biological behavior of ovarian cancer cells." (PMID 38468232, 2024). "Mechanism researched showed that MIR503HG affected the transcriptional regulation effect of SPI1 on the downstream gene TMEFF1 by interacting with the SPI1, thereby suppressing the tumorigenicity of ovarian cancer cells." (PMID 35771155, 2022). "MIR503HG inhibited SPI1-mediated transcriptional activation of TMEFF1 by binding to SPI1, and suppressed the expression of TMEFF1, thus hindering the progression of ovarian cancer." (PMID 35771155, 2022).
ovarian carcinoma (continued). "Cox regression model was used to analyze the relationship between the prognosis of ovarian cancer patients and different clinicopathological parameters, it was found that FIGO stage, ST14 expression, and TMEFF1 expression affected the survival time (P = 0.012, 0.005, 0.001, respectively)." (PMID 38468232, 2024). "TMEFF1 promotes cell proliferation, migration and invasion, inhibits apoptosis through MAPK and PI3K/AKT signaling pathways, and interacts with the tumor marker protein AHNAK in ovarian cancer." (PMID 38468232, 2024). "Based on the similar biological functions of TMEFF1 and ST14, we speculate that the interaction between them might affect their function in ovarian cancer." (PMID 38468232, 2024). "The CTA NY-ESO-1, a homologous family member of TMEFF1, can induce a higher antibody titer and CD4+/CD8+ T cell immune response, with a vaccine treatment prolonging the progression-free survival of patients with advanced ovarian cancer." (PMID 34475991, 2021).
brain tumors (3 papers, 2015 to 2024). "The expression level of TMEFF1 in brain tumor tissues is lower than that in normal brain tissues, and its overexpression inhibits the growth of brain cancer cells." (PMID 35771155, 2022). "TMEFF1 is initially reported to be differentially expressed in brain tumor tissues and normal brain tissues, and played a tumor suppressor role in brain cancer." (PMID 35771155, 2022). "In tumor research, TMEFF1 acts as a tumor suppressor gene in brain tumors." (PMID 38468232, 2024). "Initially, TMEFF1 was identified as a tumor suppressor gene in brain tumors." (PMID 38468232, 2024).
lymph node metastasis (3 papers, 2021 to 2024). "The positive expression rate of TMEFF1 in the lymph node metastasis group was 85.7% (24/28), which was significantly higher than that in the non-lymph node metastasis group (45.0%; 18/40; P < 0.001)." (PMID 38468232, 2024). "The positive expression rate of TMEFF1 in the positive lymph node metastasis group was 100% (14 of 14), which was significantly higher than that in the negative lymph node metastasis group (72.92% [35 of 48]) (P=0.029)." (PMID 34475991, 2021).
brain cancer (2 papers, 2021 to 2022). A primary or metastatic malignant neoplasm affecting the brain. "In addition, in four kinds of brain cancer cells, TMEFF1 exhibited medium and low expression, with expression of TMEFF1 in brain cancers causing growth inhibition." (PMID 34475991, 2021).
breast carcinoma (2 papers, 2012 to 2021). "Tmeff1 inhibits Nodal signaling via binding to the Nodal co-receptor, Cripto, which is overexpressed in ~70 to 80% of invasive human breast cancer." (PMID 22748014, 2012). "Immunoblotting and quantitative PCR analyses on cultured cells validated these targets and correlated Tmeff1 expression with disease progression of TGF-β-insensitive mammary cancer." (PMID 22748014, 2012).
CNS cancer (2 papers, 2007 to 2021). "Some genes already described as related to glioma's invasion capacity by microarray studies such as SPOCK1, BCL2L2, EEF1A2 and TMEFF1 also appeared in the 50 first best triples." (PMID 17519038, 2007).
chronic myeloid leukemia (1 paper, 2021). "The KEGG enrichment analysis results showed that the signaling pathways involving TMEFF1 and its associated genes include the cell cycle, Hippo signaling, spliceosome, RNA transport, and chronic myeloid leukemia pathways." (PMID 34475991, 2021).
encephalitis (1 paper, 2024). An acute inflammatory process affecting the brain parenchyma. "Other viruses, such as HSV-2 and varicella zoster virus, which also partly use NECTIN-1 to enter cells, may cause encephalitis in TMEFF1-deficient patients." (PMID 39048830, 2024).